GAGE12H (G antigen 12H)
Synonyms: OTTHUMG00000024149
Tractability: Antibody: the Human Protein Atlas places it where antibodies can reach.
Gene: Protein-coding gene on chromosome X (49,579,949 to 49,587,301, forward strand). Ensembl gene ENSG00000224902.
Subcellular location (Human Protein Atlas): Plasma membrane; Cytosol; Golgi apparatus
Homologues: Orthologues: chimpanzee GAGE10 (82% identical). Paralogues in human: GAGE12C (99% identical), GAGE12D (99% identical), GAGE12E (99% identical), GAGE12F (98% identical), GAGE12G (98% identical), GAGE1 (97% identical), GAGE12J (97% identical), GAGE13 (97% identical), GAGE2A (95% identical), GAGE2E (92% identical), GAGE10 (89% identical), PAGE1 (51% identical), and 10 more.
Diseases named in the same sentence as GAGE12H in open-access papers:
GAGE12H is named in the same sentence as 2 diseases in open-access papers, as found by Europe PMC text mining. Sharing a sentence is not in itself a finding about the gene and the disease. The quoted sentences say what the papers report.
cancer (1 paper, 2019). A tumor composed of atypical neoplastic, often pleomorphic cells that invade other tissues. "GAGE12H was found to be strongly upregulated in our system; however, TCGA data show that throughout the tumor samples, there are only a few which display a strong upregulation of GAGE12H across all cancer types, indicating random or patient-dependent alterations." (PMID 30918060, 2019).
GAGE12H also shares sentences with these, for which no sentence is quoted: tumor (1 paper).